GIGYF2 (GRB10 interacting GYF protein 2)
Description:
Key component of the 4EHP-GYF2 complex, a multiprotein complex that acts as a repressor of translation initiation. In the 4EHP-GYF2 complex, acts as a factor that bridges EIF4E2 to ZFP36/TTP, linking translation repression with mRNA decay. Also recruits and bridges the association of the 4EHP complex with the decapping effector protein DDX6, which is required for the ZFP36/TTP-mediated down-regulation of AU-rich mRNA. May act cooperatively with GRB10 to regulate tyrosine kinase receptor signaling, including IGF1 and insulin receptors. In association with EIF4E2, assists ribosome-associated quality control (RQC) by sequestering the mRNA cap, blocking ribosome initiation and decreasing the translational load on problematic messages. Part of a pathway that works in parallel to RQC-mediated degradation of the stalled nascent polypeptide. GIGYF2 and EIF4E2 work downstream and independently of ZNF598, which seems to work as a scaffold that can recruit them to faulty mRNA even if alternative recruitment mechanisms may exist. (Microbial infection) Upon SARS coronavirus-2/SARS-CoV-2 infection, the interaction with non-structural protein 2 (nsp2) enhances GIGYF2 binding to EIF4E2 and increases repression of translation initiation of genes involved in antiviral innate immune response such as IFNB1.
Synonyms: KIAA0642; PERQ2; TNRC15; GYF2; PARK11; PERQ3
Tractability: PROTAC: UniProt records ubiquitination sites on it; ubiquitination databases record sites on it; its protein half-life has been measured; a small molecule that binds it is known.
Gene: Protein-coding gene on chromosome 2 (232,697,259 to 232,860,605, forward strand). Ensembl gene ENSG00000204120.
Subcellular location (Human Protein Atlas): Cytosol
Gene Ontology:
Molecular function: cadherin binding; molecular adaptor activity; proline-rich region binding; protein binding; RNA binding; mRNA regulatory element binding translation repressor activity
Biological process: insulin-like growth factor receptor signaling pathway; mRNA destabilization; negative regulation of translation; negative regulation of translational initiation; negative regulation of type I interferon-mediated signaling pathway; post-transcriptional gene silencing; rescue of stalled ribosome; pre-mRNA catabolic process
Cellular component: cytoplasmic stress granule; cytosol; endoplasmic reticulum; endosome; Golgi apparatus; membrane; perikaryon; protein-containing complex; proximal dendrite; vesicle; cytoplasm
Genetic constraint (gnomAD): Loss-of-function variants: 12 observed, 129.67 expected, observed/expected ratio (o/e) 0.0925, 90% interval 0.058 to 0.15. The upper end of that interval is the gene's LOEUF score, 0.15, which puts it in group 1 of 6, group 1 being the genes least tolerant of losing a copy. Missense variants: 919 observed, 1,099.9 expected, observed/expected ratio (o/e) 0.84, 90% interval 0.79 to 0.88. Synonymous variants: 353 observed, 371.39 expected, observed/expected ratio (o/e) 0.95, 90% interval 0.87 to 1.04.
Homologues: Orthologues: chimpanzee GIGYF2 (99% identical), macaque GIGYF2 (99% identical), dog GIGYF2 (97% identical), guinea pig GIGYF2 (95% identical), rat Gigyf2 (95% identical), mouse Gigyf2 (94% identical), rabbit GIGYF2 (93% identical), pig GIGYF2 (78% identical), tropical clawed frog gigyf2 (64% identical), zebrafish gigyf2 (63% identical), Drosophila melanogaster Gyf (26% identical), Caenorhabditis elegans gyf-1 (20% identical). Paralogues in human: GIGYF1 (42% identical).